EZH2 (enhancer of zeste 2 polycomb repressive complex 2 subunit)
Diseases named in the same sentence as EZH2 in open-access papers (continued):
Sharing a sentence is not in itself a finding about the gene and the disease.
Burkitt lymphoma (continued). "In conclusion, our study provides compelling evidence for the therapeutic potential of simultaneous EZH2 and BTK targets in Burkitt’s lymphoma." (PMID 37752998, 2023). "In Burkitt lymphoma, MYC can stimulate enhancer of zeste homolog 2 (EZH2) expression by suppressing its negative regulator miR-26a." (PMID 35120580, 2022). "We observed an increase in PD-L1 expression with EZH2 inhibition, regardless of the presence of immune cells although Burkitt’s lymphoma is a PD-L1 negative tumor." (PMID 40308579, 2025). "To evaluate this, we performed EZH2 depletion in representative MYC(N)-driven small cell carcinoma NCI-H526 and NCI-H82 cells as well as MYC-driven Burkitt’s lymphoma Daudi cells, which are characterized by MYC(N) overexpression due to chromosome amplification or translocation." (PMID 35013218, 2022). "In addition, overexpressed enzymes like PHGDH and PSAT1 promote the MYC/miR-494/enhancer of zeste homolog 2 (EZH2) feed-forward loop and are at least partially driven by MYC/ATF4 signaling in Burkitt lymphoma cells to sustain metabolic reprogramming." (PMID 36582785, 2022). "Given that EBV infections manifest in all cases of NKTL as well as in some cases of Burkitt lymphoma and DLBCL, anti-EBV treatment may well complement EZH2-based therapeutics." (PMID 31752930, 2019). "Furthermore, Burkitt’s lymphoma is a PD-L1 negative tumor; however, treatment with the EZH2 degrader resulted in a slight increase in PD-L1 expression." (PMID 40308579, 2025). "In Burkitt lymphoma (BL), KLF4 acts as a tumor suppressor by reducing MYC expression and its downstream target EZH2 while activating tumor suppressors such as TXNIP." (PMID 39995670, 2025). "Furthermore, expression levels of EZH2 and c-MYC in liver tissue were reduced in the dEZH2-treated group compared to control, suggesting that dEZH2 maintains EZH2 degradation activity in vivo and effectively inhibits the progression of Burkitt’s lymphoma." (PMID 40308579, 2025). "However, the role of EZH2 in PD-L1 expression in Burkitt’s lymphoma has not been investigated." (PMID 40308579, 2025).
pulmonary fibrosis (18 papers, 2014 to 2025). Chronic progressive interstitial lung disorder characterized by the replacement of the lung tissue by connective tissue, leading to progressive dyspnea, respiratory failure, or right heart failure. "Direct or indirect inhibition of MTase EZH2 could therefore lead to a reduction in lung fibrosis and relieve cytokine imbalance, both associated with negative disease outcomes, and thereby contribute to the resolution of acute and long‐term effects of COVID‐19." (PMID 35833542, 2022). "Together, these studies highlight that EZH2 and G9a can be dually targeted to relieve the H3K27me3 and H3K9me3-driven repression of anti-fibrotic genes in lung fibrosis." (PMID 37476157, 2023). "They further confirmed that blockade of EZH2 with 3-DZNep not only alleviated the LPS-induced lung injury and inflammation through inducing M2 macrophages but also prevented against pulmonary fibrosis." (PMID 35432300, 2022). "In the present study, we further confirmed that blockade of EZH2 with 3-DZNeP not only lessens the LPS-induced lung injury and inflammation but also prevents against pulmonary fibrosis." (PMID 34217280, 2021). "However, it remains unknown whether EZH2 is involved in ARDS-associated pulmonary fibrosis." (PMID 34217280, 2021). "In fibroblasts from human lung affected with idiopathic pulmonary fibrosis, TGF-β1 treatment significantly increases the association of EZH2 to its target gene and reinforces epigenetic repression." (PMID 33391480, 2021). "EZH2 is also overexpressed in renal fibrosis 11-13, idiopathic pulmonary fibrosis (IPF) 14, 15, and systemic sclerosis (SSc) 16, a prototypical idiopathic fibrotic disease, its inhibition by DZNep attenuates these fibrotic conditions." (PMID 33391480, 2021). "In this study, we examined the effect of the EZH2 inhibitor on LPS-induced pulmonary fibrosis in mice and explored the possible mechanism involved." (PMID 34217280, 2021). "We also examined the EZH2 expression in the lung tissues of a bleomycin‐induced murine lung fibrosis model." (PMID 27582065, 2016). "To determine the in vivo effect of EZH2 inhibition on lung fibrosis, we intraperitoneally administered DZNep to the mice daily beginning 1 day before the bleomycin challenge." (PMID 27582065, 2016). "Immunohistochemical analysis using EZH2 antibodies showed a strong staining in the bleomycin group, whereas the signals were virtually undetectable in the control group, suggesting that the EZH2 protein is also upregulated in bleomycin‐induced lung fibrosis." (PMID 27582065, 2016). "Enhances EMT, contributing to lung fibrosis by targeting β‐catenin and EZH2." (PMID 40895189, 2025). "On the other hand, EZH2 expression is associated with enhanced TGF-β-induced differentiation of pulmonary fibroblasts into myofibroblasts and, consequently, pulmonary fibrosis as well as with the ability of TGF-β to promote the migration and differentiation of atrial myofibroblasts." (PMID 35108527, 2022). "We speculate the function of Ezh2 in inducing the increase of H3K27me3 at Fbxw7 promotor and silencing of Fbxw7 gene might also be involved in regulating pulmonary fibrosis." (PMID 35069531, 2021). "Next, we set out to elucidate the role of EZH2 in mediating pulmonary fibrosis induced by LPS." (PMID 34217280, 2021). "In this study, we investigated the role and mechanisms of EZH2 in pulmonary fibrosis in a murine model of LPS-induced ARDS and in ex-vivo cultured alveolar macrophages (MH-S) and mouse lung epithelial cell line (MLE-12) by using 3-deazaneplanocin A (3-DZNeP) and EZH2 the small interfering (si) RNA." (PMID 34217280, 2021). "This suggests that EZH2 is a critical mediator of EMT in LPS -induced lung fibrosis." (PMID 34217280, 2021).
pulmonary fibrosis (continued). "Targeting EZH2 may be a potential therapeutic strategy to prevent and treat pulmonary fibrosis post ARDS." (PMID 34217280, 2021). "In vivo studies showed that the inhibition of EZH2 by DZNep reduced pulmonary fibrosis." (PMID 27582065, 2016). "Snitow reported that EZH2 loss reduces the expression of myocardin and TBX18, thereby affecting the autonomic inhibition of smooth muscle differentiation in mesothelium cells, and ultimately contributing to the development of COPD and idiopathic pulmonary fibrosis." (PMID 38114929, 2023). "Recent studies suggest that enhancer of zest homolog 2 (Ezh2) may increase H3K27me3 methylation at the Fbxw7 promoter, potentially repressing Fbxw7 expression, while IL-4 could reduce Fbxw7 activity to inhibit c-Jun degradation in fibrotic environments, thereby impacting pulmonary fibrosis." (PMID 40901482, 2025). "EZH2 works in coordination with the histone methyltransferase enzyme, H3K9 HMT G9a, to repress anti-fibrotic genes in lung fibrosis." (PMID 37476157, 2023). "Inhibition of the enhancer of zeste 2 PRC2 subunit (EZH2) was shown to reduce TGF‐β1‐induced human lung fibroblast‐to‐myofibroblast transformation and to attenuate bleomycin‐induced pulmonary fibrosis in mice." (PMID 35833542, 2022). "The interplay between EZH2 and G9A in regulating CXCL10 transcription has also recently been observed in idiopathic pulmonary fibrosis by Coward and colleagues, further supporting our findings." (PMID 35131874, 2022). "We found that EZH2 was upregulated in the lungs of patients with IPF and in mice with bleomycin‐induced lung fibrosis." (PMID 27582065, 2016). "In addition, EZH2 was reported to be upregulated in IPF patients and in bleomycin‐induced lung fibrosis mouse models, and its inhibition following lung injury has been shown to attenuate fibrosis." (PMID 38494860, 2024). "To our knowledge, the O‐GlcNAc regulation of EZH2/gene expression in lung fibrosis has not been examined; therefore, we explored whether this regulatory mechanism applied to lung fibroblasts and would contribute to the pathogenesis of lung fibrosis." (PMID 38494860, 2024).
rhabdomyosarcoma (18 papers, 2012 to 2025). A rare aggressive malignant mesenchymal neoplasm arising from skeletal muscle. "A large number of human cancers, such as rhabdomyosarcoma, are associated with abnormally high levels of EZH2 compared to corresponding normal tissue." (PMID 34372908, 2021). "• This study reveals deregulation of miR-26a and Ezh2 in rhabdomyosarcoma samples and cell lines, suggesting their potential involvement in rhabdomyosarcoma pathogenesis." (PMID 38826780, 2024). "The results of this study demonstrate the potential utility of combining EZH2 inhibitors with differentiation agents for the treatment of paediatric rhabdomyosarcomas." (PMID 37858275, 2023). "In rhabdomyosarcoma (RMS), increased EZH2 protein levels are associated with poor prognosis and increased metastatic potential, suggesting EZH2 as a therapeutic target." (PMID 35008205, 2021). "Rhabdomyosarcoma (RMS) show increased abundance of Enhancer of Zeste Homologue 2 protein (EZH2), a catalytic subunit of the polycomb repressive complex 2 (PCR2), and altered epigenetic markers compared to skeletal muscle." (PMID 35008205, 2021). "By using pharmacological inhibition of EZH2, the aggressiveness of rhabdomyosarcoma is less with a more differentiated phenotype." (PMID 28401060, 2017). "This provides further treatment options for rhabdomyosarcoma by using EZH2 inhibitors as adjuvant therapy, thus with a likely possibility of increasing the effectiveness of current conventional treatment." (PMID 28401060, 2017). "At the post-transcriptional level, microRNAs are likely to modulate EZH2 levels, since EZH2 is a validated target of the promyogenic miR-26a, and high expression of EZH2 was consistently paralleled by suppression of miR-26a in rhabdomyosarcoma." (PMID 23110793, 2012). "A recent study demonstrated that EZH2 inhibition is able to reverse the tumor phenotype of embryonic rhabdomyosarcoma RD cell lines and in alveolar rhabdomyosarcoma cell lines, even in the presence of proliferative stimuli, such as the addition of serum to growth conditions." (PMID 34372908, 2021). "Notably, it has been observed that in various cancers, including Rhabdomyosarcoma, there is over-expression of the catalytic subunit of the PRC2 complex, enhancer of zeste homolog 2 (EZH2), and its expression is linked to advanced disease stages and poor prognosis." (PMID 34372908, 2021). "Next, we performed in silico gene expression analysis of PRAME, EZH2, and the RAR genes in synovial, leiomyosarcoma, rhabdomyosarcoma, and liposarcoma STS cell lines." (PMID 39550391, 2024). "A direct interaction between EZH2 and GATA4 was also observed in rhabdomyosarcoma, a type of soft tissue sarcoma that develops from muscle or fibrous tissue, and a rare type of sarcomas of the heart." (PMID 37664059, 2023). "Several molecules capable of inducing inhibition of EZH2 catalytic activity (TPA, GSK126, DZNep, MC1945, MC1948) have been tested in recent years in embryonic rhabdomyosarcoma cells." (PMID 34372908, 2021). "Additional studies have shown that depletion of JARID2 mRNA or inhibition of EZH2 led to increases in MYOG mRNA and differentiation-specific gene expression in rhabdomyosarcoma (RMS) cell lines." (PMID 30119689, 2018). "Indeed, there are currently no drugs able to inhibit the catalytic activity of EZH2 in the clinical field for the treatment of Rhabdomyosarcoma." (PMID 34372908, 2021). "Parenthetically, YY1 in this collaboration with JARID2 can recruit EZH2 and HDAC 1 to the promoter region leading to a block in differentiation, partially via the downregulation of miR-29b2 and miR-29c and by inhibiting MyoD, favoring rhabdomyosarcoma cell proliferation over differentiation." (PMID 27323832, 2016). "To test this approach, we carried out a proof-of-concept study using EZH2 as a target for knockout in SMARCB1-negative (G-401) MRT cell line and SMARCB1-wild type (RD) rhabdomyosarcoma cell line; the former but not latter are sensitive to inhibition of EZH2." (PMID 26578851, 2015).
mantle cell lymphoma (17 papers, 2015 to 2024). Mantle cell lymphoma is a rare form of malignant non-Hodgkin lymphoma affecting B lymphocytes in the lymph nodes in a region called the ``mantle zone''. "Genome-wide mapping of EZH2 binding domains shows EZH2 binds the HOXA cluster and EZH2 overexpression in mantle cell lymphoma has been associated with hypermethylation over the HOXA cluster." (PMID 36064314, 2022). "Wang’s study suggested that MALAT1 over-expression increases the proliferation of mantle cell lymphoma (MCL) cells by activating EZH2 and inhibiting p21 and p27 genes in vitro." (PMID 28561778, 2017). "EZH2 is also strongly expressed in mantle cell lymphomas where high EZH2 expression is correlated with aggressiveness and poor prognosis." (PMID 26497210, 2016). "lncRNA MALAT1 has already been reported to bind with EZH2 in mantle cell lymphoma." (PMID 31830649, 2020). "A relevant effect of EZH2 on DNA methylation was observed precisely at the HOX loci in mantle cell lymphoma (MCL) and chronic lymphocytic leukemia (CLL)." (PMID 26029238, 2015). "In mantle cell lymphoma, HOX genes are silenced by H3K27me3 chromatin methylation mediated by overexpression of EZH2." (PMID 35145272, 2022). "MALAT1 is upregulated in tumour tissues from mantle cell lymphoma (MCL) patients compared to normal B-cells, and knockdown of MALAT1 results in cell cycle arrest due to upregulation of p21 and p27 through enhancer of zeste homolog 2 (EZH2), a component of the polycomb repressive complex 2 (PRC2)." (PMID 30134619, 2018). "Expression of EZH2 has not been assessed systematically in mantle cell lymphoma (MCL)." (PMID 34376807, 2021).
Myelodysplasia (17 papers, 2011 to 2025). Clonal hematopoietic stem cell disorders characterized by dysplasia (ineffective production) in one or more hematopoietic cell lineages, leading to anemia and cytopenia. "This was supported by in vitro experiment data, the flanking sequence of the cassette exon that promotes binding of U2AF1 S34 mutant protein, and the mutational landscape of myelodysplasia in which EZH2 and U2AF1 S34 mutations were mutually exclusive." (PMID 30194306, 2018). "This supports the pathogenic role of the splicing alteration of EZH2 in the U2AF1 S34-mutated myelodysplasia." (PMID 30194306, 2018). "In another model, concurrent deletion of Tet2 and Ezh2 cooperated to cause more advanced myelodysplasia and accelerated the development of myeloid disorders including MDS/MPN." (PMID 30450160, 2018). "In particular, the adverse-risk group has been expanded to include seven additional mutations: BCOR, EZH2, SF3B1, SRSF2, STAG2, U2AF1, and ZRSR2—together with ASXL1 and RUNX1 (already included in ELN 2017)—forming the “myelodysplasia-related” (MR) gene group." (PMID 41464583, 2025). "Concurrent TET2 and EZH2 deletion is sufficient to induce an MDS/myeloproliferative phenotype in mice, and in a RUNX1 mutant model, EZH2 loss promotes myelodysplasia development but inhibits transformation to AML." (PMID 36902450, 2023). "The presence of mutations in at least one gene associated with myelodysplasia (i.e., SRSF2, SF3B1, U2AF1, ZRSR2, ASXL1, EZH2, BCOR, or STAG2) was significantly more frequent in older patients." (PMID 35805006, 2022). "The EZH2 mutation rate in the different AML subgroups was 12% (3/25) in de novo AML, 9% (2/22) in AML with myelodysplasia-related changes (MRC), and 25% (1/4) in therapy-related AML (t-AML)." (PMID 33845873, 2021). "Ezh2 knockout mice (Ezh2−/−) developed myelodysplastic disorders characterized by anemia, splenomegaly, and dysplasia of the bone marrow, and the concurrent loss of both Tet2 and Ezh2 resulted in either an MDS phenotype (pancytopenia, myelodysplasia) or MDS/MPN phenotype (monocytosis, splenomegaly)." (PMID 38396286, 2024). "Seventy-nine patients, or 45% of all re-classified patients, were moved from ELN-2017 favorable (n = 11) or intermediate (n = 68) to ELN-2022 adverse risk based on the inclusion of additional myelodysplasia-related (MR) mutations (BCOR, EZH2, SF3B1, SRSF2, STAG2, U2AF1, ZRSR2) as poor-risk markers." (PMID 37041198, 2023). "Mice models have revealed that EZH2 or TET2 deficiency alone is sufficient to induce an MDS/MPN phenotype with lethality, while depletion of both EZH2 and TET2 synergistically induces myelodysplasia and strengthens the progression of both MDS and MDS/MPN." (PMID 36338673, 2022). "While increased transformation to acute leukemia from myelodysplasia in EZH2-deleted cases has not been demonstrated, pre-leukemic changes associated with MDS coupled with other changes may predispose patients to the development of AML." (PMID 28918518, 2017).
head and neck cancer (16 papers, 2013 to 2025). A primary or metastatic malignant neoplasm affecting the head and neck. "EZH2 as the core member of PRC2 has been linked to multiple aggressive cancers including head neck cancers." (PMID 24345883, 2013). "A recent study showed that an EZH2 inhibitor enhanced antigen presentation and overcame resistance to anti-PD-1 therapy in head and neck cancer." (PMID 39941725, 2025). "We conclude that CCND1, AXL, CDKN2A, TERT, and EZH2 are the hub genes involved in cisplatin resistance in head and neck cancer that have significant mRNA expression and effect on overall survival." (PMID 36715825, 2023). "We analyzed EZH2 mRNA expression in a well-characterized dataset of 230 (110 original and 120 validation cohorts) human head and neck cancer samples." (PMID 30469511, 2018). "Accumulating evidence has indicated that EZH2 serves as an essential oncogenic driving force during the initiation and progression of head neck cancers." (PMID 27793210, 2016). "Accumulating evidence has indicated that EZH2 serves as an essential oncogenic driver during the initiation and progression of head neck cancers." (PMID 24345883, 2013). "Moreover, researchers demonstrated that E3 ligase CHIP can mediate EZH2 ubiquitination degradation and subsequently derepress EZH2-silenced tumor suppressor genes by attenuating the H3K27me3 level in head and neck cancer cells." (PMID 33308321, 2020). "Moreover, EZH2 has been found to promote malignant transformation of oral leukoplakia, epithelial to mesenchymal transition and cancer stem cell maintenance in head neck cancers." (PMID 24345883, 2013). "However, Nienstedt's study found a relatively low percentage of EZH2 expression in tongue cancer (6%) compared to other cohorts (39–100%), indicating potential differences in the molecular environment among different mucosal regions of head and neck cancer that could influence EZH2." (PMID 38600608, 2024). "Increased DNA methyltransferase 1 (DNMT1) and enhancer of zeste homolog 2 (EZH2) levels, along with increased histone H3 lysine 27 trimethylation (H3K27me3) levels, correlated with decreased levels of PTEN in radioresistant head and neck cancer cells." (PMID 33919657, 2021). "Targeting EZH2, via the use of EZH2 inhibitors GSK126 and EPZ6438, enhanced antigen presentation, antitumor immunity in head and neck cancer." (PMID 34930302, 2021). "Overexpression of EZH2 significantly correlated with tumor size, cervical lymph node metastasis, clinical stage and poor prognosis, and served as an independent prognostic indicator for patients with head neck cancer." (PMID 24345883, 2013).